TNF (tumor necrosis factor)
Diseases named in the same sentence as TNF in open-access papers (continued):
Sharing a sentence is not in itself a finding about the gene and the disease.
psoriasis (continued). "E130307A14-Rik was overexpressed by delivering E130307A14-Rik and SRSF10 lentivirus into a mouse model of psoriasis, and significantly inhibited IL−17A- and TNF-α-induced pro-inflammatory effects." (PMID 37310201, 2023). "Th17 cells and their secreted cytokines, such as IL-17A, IL-23, and TNF-α, play a role in a variety of chronic inflammatory illnesses, including psoriasis." (PMID 37643205, 2023). "The immune dysregulation in psoriasis involves overactive T helper type 1 (Th1) and Th17 responses, leading to the production of pro-inflammatory cytokines such as tumor necrosis factor-alpha (TNF-α), interferon-gamma (IFN-γ), and interleukin-17 (IL-17)." (PMID 37700026, 2023). "The findings of a large number of genome-wide association studies (GWAS) and clinical trials support the central role of TNF-IL-23-IL-17 signaling pathways in the pathogenesis of psoriasis, especially for plaque psoriasis." (PMID 38008779, 2023). "Specific cells (such as T cells) have been observed to play an obvious role in the pathogenesis of psoriasis, in addition to specific immunological molecules such as TNF-, IL-12, IL-23, IL-17, and other molecules that can aid in the pathogenesis of psoriasis." (PMID 36995575, 2023). "The risk of myocardial infarction was also reduced in psoriasis patients treated with TNF-α inhibitors compared with psoriasis patients treated with topical therapy and MTX." (PMID 38149053, 2023). "Studies highlight the pivotal role of cytokines such as TNF-α, IL-23, and IL-17 in the development and persistence of psoriasis." (PMID 38239358, 2023). "Even the relatively low-potency DXM group exhibited a similar ability to inhibit the protein expression of the IL-23/IL-17/TNF-α axis in psoriasis-like skin when compared with high-potency steroids such as ESP and CLO." (PMID 37631230, 2023). "In agreement with our study, psoriatic skin-treated with ScF had a significantly low levels of mTOR protein alongside the downregulation of TNF-α, IL-1β, and IL-17 indicating an inhibitory effect of ScF on mTOR signaling to mitigate psoriasis severity." (PMID 37495626, 2023). "The immune axis of tumor necrosis factor (TNF)-α/interleukin (IL)-23/IL-17 is involved in the pathogenesis of psoriasis." (PMID 37685519, 2023). "SAMHD1, C10orf99, and AKR1B10: the highly dysregulated genes in resolved epidermis are known to be associated with pathogenesis of psoriasis, and the DRTP was enriched in WNT, TNF, and mTOR signaling pathways." (PMID 36901987, 2023). "Biological therapies, such as tumor necrosis factor (TNF), interleukin (IL)-17 and IL-23 inhibitors and small molecules allow dermatologists to successfully treat moderate-to-severe psoriasis and improve patients’ QoL." (PMID 38202108, 2023). "Consistent with this, we now demonstrate that the strongest IL-17A and TNF downstream responses in psoriasis are in the supraspinous compartment." (PMID 37308489, 2023). "TNFα, is secreted by both T cells and antigen-presenting cells within psoriasis skin lesion, more over TNF antagonists become a new modality in treatment of moderate-to-severe psoriasis." (PMID 37531036, 2023). "In conclusion, the NLR, MLR, PLR and CRP values significantly reduced after treatment with TNF-α inhibitors in patients with psoriasis." (PMID 36769622, 2023). "The first biologics for treating psoriasis were tumor necrosis factor (TNF)-α inhibitors, which target TNF-α from Th1 cells." (PMID 38137722, 2023). "During the onset of psoriasis, external stimuli trigger the recruitment and activation of immune cells to secrete cytokines such as IL-17, IL-22, TNF-α, and INF-γ, which promote keratinocyte proliferation." (PMID 37762693, 2023). "This is consistent with the efficacy of biologics targeting IL-17, IL-23, and TNF in this loop in type 17 EIME in psoriasis." (PMID 37841246, 2023).
psoriasis (continued). "It was observed that luteolin improved psoriasis-like skin lesions via suppressed infiltration by immune cells and downregulation of IL-6, IL-1β, TNF-α, IL-17A, and IL-23 expression." (PMID 37047297, 2023). "TNF-α inhibitors are the first biological agents approved for the treatment of moderate-to-severe psoriasis and psoriatic arthritis." (PMID 38008779, 2023). "We first evaluated the achievement rates of PASI 75, 90 and absolute PASI ≤ 2 during the treatment with individual TNF-α inhibitors in patients with psoriasis." (PMID 36769622, 2023). "While the histopathologic aspects were similar, these reactions were considered distinct immunological entities with Th1/IFN-γ/IFN-α characteristics; all the anti-TNF-induced lesions showed a more robust IFN-γ activation than in psoriasis or eczema." (PMID 37175894, 2023). "In fact, it has been shown that classical psoriasis is a T-cell-mediated autoimmune disease driven by TNF." (PMID 37175894, 2023). "Patients with both psoriasis and congestive heart failure should be treated with IL-17 and IL-23 inhibitors with the recommendation to avoid TNF-α inhibitors in NYHA class III or IV." (PMID 37631384, 2023). "The regulation of IL-17A and TNF-α engages distinct pathogenetic mechanisms, with IL-17A/IL-23 as the primary pathogenetic axis in psoriasis, while TNF-α assumes a supportive role." (PMID 38239345, 2023). "Our results suggest that patients with moderate-to-severe psoriasis under treatment with TNF inhibitor drugs or UTK show greater pharmacological survival of UTK." (PMID 37240048, 2023). "Lactobacillus probiotics have been successfully used in vitro in imiquimoid-induced psoriasis in mice, resulting in lower gene expression levels of pro-inflammatory markers such as TNF-α, IL-19, IL-17A, and IL-23, as well as lower PASI scores." (PMID 37895330, 2023). "Although the application of biological agents that target IL−17A, IL−23, or TNF-α significantly improved the treatment of psoriasis, they cannot completely eliminate the disease." (PMID 37310201, 2023). "A systematic review from 2016 found that the risk of cardiovascular events was markedly decreased in the TNF inhibitor group compared with MTX treatment in PsA and psoriasis patients (RR 0.67, 95% CI 0.52–0.88)." (PMID 37109438, 2023). "Psoriasis has been widely studied in the last few decades, and several therapeutic approaches were developed to target specific cells (T cells), chemokines (TNFα), and interleukins (IL‐17 and IL‐23) for treatment." (PMID 37226685, 2023). "This leads to the transcription of various inflammatory signals, such as proinflammatory cytokines (TNF-α, IL-1, IL-6), chemokines, and Toll-like receptor ligands, which can contribute to the inflammatory process in psoriasis." (PMID 38203337, 2023). "Leptin has been shown to increase the synthesis of pro-inflammatory mediators involved in the pathogenesis of psoriasis, such as IL-1, IL-6, TNF-α, and CXCL8." (PMID 36675592, 2023). "In psoriasis patients, IL-22 acts synergistically with IL-17, TNF-α and other cytokines to maintain the inflammatory response in psoriasis." (PMID 37270497, 2023). "The IL-17+ CD8+ T cells were accumulated in lesional skin of psoriasis and able to release TNFα, IL-17 and IFN-γ, resulting in promoting inflammatory process." (PMID 37942312, 2023). "Pomalidomide was also predicted to be a potential anti-psoriasis drug because it inhibits TNF-α production." (PMID 37035327, 2023). "Nevertheless, we obtained important and representative results which show the influence that certain genetic polymorphisms have on the probability of changing treatment with anti-TNF drugs or UTK in patients with moderate-to-severe psoriasis." (PMID 37240048, 2023). "TNF-α inhibitors are the oldest agents approved for the treatment of psoriasis and psoriatic arthritis, and their long-term safety profile is well-known." (PMID 37239484, 2023).
psoriasis (continued). "Another study on an imiquimod-induced psoriasis mouse model also evaluated skin permeation, deposition and anti-inflammatory effect of the hybrid lipidic nanoparticles loaded with siRNA against tumor necrosis factor and capsaicin." (PMID 36986611, 2023). "The synergistic action of TLR7 and imiquimod (IMQ, a TLR7 ligand) induces both the cytokines required to activate the Th17 pathway and the proinflammatory factor expression for psoriasis pathogenesis, and promotes IL-1, IL-2, and TNF-α production by DCs." (PMID 37160878, 2023). "SIRT3 deficiency exacerbated the TLR7/8-XBP1s response via deacetylation activity targeting XBP1s, contributing to the transcription of proinflammatory cytokines IL-23, IL-6, and TNF-α and thus promoting psoriasis progression and disease severity." (PMID 37275851, 2023). "While TNF-α inhibitors have been proven to be effective in the majority of psoriasis patients, various cutaneous adverse reactions have been reported, such as erythema, vasculitis, edema, bullous lesions, and lichen planus-like dermatitis." (PMID 37664349, 2023). "Human IL-37b inhibits the production of CXCL8, IL-6, and S100A7, which are important in the pathogenesis of psoriasis, in keratinocytes stimulated with inflammatory cytokines (TNF-α, IL-17A, IL-22, IL-1α, and Oncostatin-M)." (PMID 37834081, 2023). "Resistin was shown to correlate with the severity of psoriasis and to enhance the production of tumor necrosis factor-α (TNF- α) and interleukin-6 (IL-6), both of them being part of the pathogenesis of psoriasis." (PMID 37895330, 2023). "Immune-related cells such as dendritic cells (DCs) and macrophages, as well as Toll-like receptors and cytokines such as interferon (IFN)- α, TNF-α, IFN-ɤ, IL-12, IL-22, IL-23, and IL-17, are closely associated with psoriasis pathogenesis." (PMID 37072847, 2023). "Leptin increases the synthesis of pro-inflammatory mediators that play an important role in the development of psoriasis, such as TNF-α and CXCL8." (PMID 36675592, 2023). "Psoriasis features an enhanced tumor necrosis factor (TNF)-α–interleukin-23 (IL-23)–IL-17 immune axis and exaggerated proliferation and abnormal differentiation of epidermal keratinocytes." (PMID 37762500, 2023). "Previous research indicated that interleukin-17A (IL-17A), interleukin-22(IL-22), tumor necrosis factor-α (TNF-α), and interleukin-1α (IL-1α) were pro-inflammatory cytokines in psoriasis and linked with NF-κB signalling activation." (PMID 37636269, 2023). "Macrophages play a crucial role in the progression of psoriasis and are a major source of TNF-α in psoriatic lesions." (PMID 37554338, 2023). "Biologics targeting inflammatory cytokines such as tumor necrosis factor (TNF)-α and interleukins (ILs) 12/23/17 have been used in the treatment of psoriasis." (PMID 35814239, 2022). "TNF-α inhibitors (etanercept, adalimumab, and infliximab) are human fusion proteins used in treatment psoriasis." (PMID 35313642, 2022). "Plasma concentrations of proinflammatory molecules in patients with SARS-CoV-2 are higher than those in healthy controls, including IL-12, IL-17 and TNF-α, which play an important role in the pathogenesis of psoriasis." (PMID 36016267, 2022). "IL-17, the major effector cytokine in psoriasis, acts alone or synergistically with TNF-α to induce the expression and release of many psoriasis-related proteins from keratinocytes, such as β-defensin 4 and S100A7." (PMID 35884790, 2022). "Several studies have shown that TNF-alpha inhibitors improve endothelial function in psoriasis (e.g., improved aortic stiffness, decreased sCAMs)." (PMID 35883760, 2022). "Macrophages play a critical role in the maintenance of skin inflammation in psoriasis by the effective recruitment and activation of macrophages with sufficient release of TNF-α." (PMID 35216231, 2022).
psoriasis (continued). "Accumulating evidence demonstrates the role of NLRP3 in psoriasis patients, with potential reductions in disease activity and fatigue from mediating pro-inflammatory cytokines (e.g., IL-1β and TNF-alpha) regulated by the NLRP3 inflammasome." (PMID 35663672, 2022). "Biologics such as tumor necrosis factor (TNF), IL-12/23, IL-17 and IL-23 inhibitors have allowed dermatologists to successfully treat moderate-to-severe psoriasis." (PMID 35628929, 2022). "Of note, treatment with the anti-TNF-α drugs etanercept and adalimumab, commonly used in the treatment of psoriasis, was shown to exert positive effects on insulin sensitivity." (PMID 36012327, 2022). "Studies in patient cohorts have demonstrated an association of the inflammatory mediators involved in the pathogenesis of AD and psoriasis, such as tumor necrosis factor (TNF)-α, interleukin (IL)-1, and IL-6, with depression or anxiety disorders." (PMID 35806489, 2022). "Of note, among these 23 patients, one patient with articular paradoxical articular manifestation, had also a paradoxical cutaneous psoriasis induced by anti-TNFα, but years later." (PMID 35091460, 2022). "It was also reported that in psoriasis patients, IL-17 will then synergize with TNF to intensify inflammatory response." (PMID 35770187, 2022). "Despite psoriasis studies on pathogenesis had clarified several aspects, from a therapeutic point of view, anti-psoriatic biological drugs antagonize TNF-α, IL-17/IL-23 pathway and, recently, also JAKs." (PMID 35056153, 2022). "25-hydroxy vitamin D downregulates the expression and production of several pro-inflammatory cytokines including TNF-α, IL-1β, IL-6, and IL-8, thereby establishing its anti-inflammatory effect on the inflammatory profile of psoriasis." (PMID 36261848, 2022). "scRNA-seq analysis showed that aberrant inflammatory transcription of A20 in KCs in psoriasis is related to the IL-17 and tumor necrosis factor-α(TNF-α) signaling pathways, suggesting a potential targeted therapy." (PMID 36505405, 2022). "The inflammatory cytokines, such as TNF-α, IL-12, IL-23, and IL-17, are increased in the peripheral blood of psoriasis patients." (PMID 36249714, 2022). "Novel biological drugs, which target TNF-α, the p40 subunit of IL-12 and IL-23, or IL-17 receptors, are effective in treating psoriasis and reducing the PASI score." (PMID 35313642, 2022). "Thereby, these specific cells excessively produce pro-inflammatory factors like TNF-α, chemokines, and interleukins that are essential to psoriasis and AD." (PMID 35669784, 2022). "Adalimumab (ADA), a TNF-α antagonist, was shown to be effective in the treatment of psoriasis, despite its possible adverse reactions." (PMID 35889927, 2022). "First, we would like to discuss the use of anti-TNFα agents, which are biologics widely administered for psoriasis as this cytokine is an important factor in psoriasis pathogenesis." (PMID 36226313, 2022). "It has however been shown that TNF-α potentiates other forms of itch and the TNF-α sequestering agent etanercept reduced dry skin itch, thus underlining its use as a treatment option in psoriasis." (PMID 36385768, 2022). "TNF-α, a cytokine commonly elevated in patients with psoriasis, promotes the transcription of MDA5 and RIG-I in keratinocytes." (PMID 36425068, 2022). "The development of new classes of biologics apart from TNF inhibitors expanded the therapeutic possibilities for psoriasis." (PMID 36614836, 2022). "It has been reported that serum levels of IL-33 were significantly increased in conditions such as psoriasis, psoriatic arthritis and pustular psoriasis, and related to TNF-α." (PMID 36498859, 2022). "Among them, TNF-α, IL-17A, and IL-23 are of central importance in psoriasis as therapies targeting them are most efficient in the treatment of patients." (PMID 35075118, 2022).
psoriasis (continued). "TNF‐α and IL‐1ß are cytokine cues that facilitate some LCs migration to local‐draining LNs; and LCs from patients with early‐onset psoriasis are stubborn to these cues, in support of their role in the pathogenesis of psoriasis." (PMID 34913478, 2022). "The importance of the TNF-α and IL-23/IL-17A axis in disease pathogenesis is well described for psoriasis and psoriatic arthritis." (PMID 35203534, 2022). "Analysis of the inflammatory factors in the serum showed that the levels of TNF-α, IL-6, IL-1β, and IL-17 were significantly higher in psoriasis patients than in HCs." (PMID 35927231, 2022). "Dysregulated inflammatory pathways and increased levels of proinflammatory cytokines, such as TNF-α, IL-6, and IL-8, are critical in the pathogenesis of psoriasis." (PMID 36110097, 2022). "A randomized controlled study reported significant reductions in IL-17 and TNF-α levels in patients with psoriasis after taking statins for eight weeks." (PMID 36035406, 2022). "Initially, Th1 cells and the cytokines produced by these cells, such as TNF-α and IFN-γ, were associated with psoriasis." (PMID 35813890, 2022). "Psoriasis is classically recognized as a pro-inflammatory state characterized by the overexpression of type 1 cytokines (TNF-α, IL-12, and IL-23)." (PMID 35805960, 2022). "Increased expression of IL-36 has been found in the skin of patients with psoriasis; in addition, inflammatory factors, such as TNF and LPS, have been shown to increase IL-36 expression." (PMID 36142901, 2022). "Inhibiting the overproduced TNF-α in severe cases of psoriasis using different inhibitors opens many discussions relating to how different clinical efficacies can result in its improved biological activities." (PMID 35203707, 2022). "NF-κB is a key transcription factor responsible for the pathogenesis of psoriasis that regulates immunity, proliferation, and apoptosis, as well as triggering the production of pro-inflammatory cytokines such as TNF-α and IL-17." (PMID 35566346, 2022). "For instance, there was evidence of the improvement observed in AD patients after administration of anti-TNFα agents for psoriasis." (PMID 35566558, 2022). "It is noteworthy that IL‐17A and TNFα were primarily considered as stimulants of IκBζ‐executed psoriasis‐like skin lesions; however, the search for additional IκBζ inducers was pursued." (PMID 36245291, 2022). "Previous studies have identified several clinical factors such as dermoscopic hemorrhagic dots and BMI at baseline that influence the response to anti-TNF-α therapy in psoriasis." (PMID 36059983, 2022). "As such, ustekinumab has been shown to be an effective treatment for TNF-a inhibitor-induced paradoxical psoriasis." (PMID 35884790, 2022). "The study population included patients with psoriasis receiving methotrexate (n=14), TNF inhibitors (n=19), IL-17 inhibitors (n=14), IL-23 inhibitors (n=20), and 15 healthy controls, who had received both vaccine doses." (PMID 34778846, 2022). "Further studies confirming the functional implication of IQGAP2/F2RL2 in psoriasis and the response to anti-TNF agents are warranted." (PMID 36059983, 2022). "Due to the important role of TNF-α in the pathogenesis of psoriasis, TNF-α blockage has been used for clinical treatment of psoriasis patients." (PMID 36618400, 2022). "Because DXM has a potent antioxidant effect, it can reduce the expression of proinflammatory cytokines, such as IL-6 and TNF-α, and inhibit inflammatory changes in psoriasis." (PMID 35629363, 2022). "Another key cytokine, which is engaged in the pathogenesis of psoriasis and also NDs, is mentioned earlier TNFα." (PMID 36226313, 2022). "Other studies evaluated the impact of TNF-α inhibitors in psoriasis on several different CV imaging biomarkers." (PMID 35686132, 2022). "Once produced, the patches were enhanced with two different -TNFα or IL-17α- blockers selected as commonly used biological factors routinely administered systematically for the treatment of psoriasis." (PMID 35742957, 2022).